TNF (tumor necrosis factor)
Diseases named in the same sentence as TNF in open-access papers (continued):
Sharing a sentence is not in itself a finding about the gene and the disease.
sarcoidosis (continued). "Two polymorphisms of TNF-α (tumor necrosis factor alpha) are associated with susceptibility to sarcoidosis in European population." (PMID 32823753, 2020). "Previous reports suggest a favorable effect of secukinumab in two cases of sarcoidosis associated with TNF antagonists." (PMID 33330556, 2020). "TNF-β and TNF-α polymorphisms are associated with susceptibility to sarcoidosis in certain populations, with TNF being a key regulator of the inflammatory response." (PMID 28253271, 2017). "Although the role of TNF-α in tumor development is not fully understood, an increased risk of malignancy with TNF-α-inhibitors has been suggested in other diseases than sarcoidosis." (PMID 23762724, 2013). "Of the 12 case-controls articles examining the association between the TNF-α gene G-307A polymorphism and sarcoidosis risk, 9 involved Caucasian populations, and 3 included Asian populations." (PMID 24244632, 2013). "In 2007, Medica and coworkers have meta-analyzed the TNF-α gene G-307A polymorphism in association with sarcoidosis, and found that this polymorphism was linked to the occurrence of sarcoidosis." (PMID 24244632, 2013). "Polymorphisms in the TNFα locus were associated with sarcoidosis phenotype and prognosis and have been linked to altered TNFα expression." (PMID 22513006, 2012). "With increasing use, evidence is collected for the association of sarcoid-like granulomatous disease developing after the initiation of anti-TNF-α therapy, with disease reversal after discontinuation." (PMID 23320239, 2012). "The TNF-α −308 G/A and −238 G/A polymorphisms were found to influence serum TNF-α levels in patients with sarcoidosis of Asian Indian population and our results are in line with this study." (PMID 23284977, 2012). "Both type I interferon (IFN), also known as IFN-α and tumor necrosis factor alpha (TNF-α) have been implicated in the pathogenesis of sarcoidosis." (PMID 22195005, 2011). "Whereas anti-TNFα therapy often suppresses sarcoidosis disease activity, one clinical variant of sarcoidosis is actually promoted by anti-TNFα therapy." (PMID 21637752, 2011). "In African-American patients with sarcoidosis, neurologic disease was associated with higher TNF-α (P = 0.041) and male sex (P = 0.049), and these two associations were independently significant." (PMID 22195005, 2011). "Multiple studies propose that psoriasis and sarcoidosis may share a TNF-α-mediated pathogenic mechanism." (PMID 41357198, 2025). "Interestingly, anti-TNF therapies have paradoxically been linked to the development or exacerbation of inflammatory conditions, including sarcoidosis." (PMID 40351964, 2025). "Additionally, the TNF-α II allele polymorphism was shown to be significantly associated with the development of EN in the setting of sarcoidosis." (PMID 41216300, 2025). "Data on an increased infection risk in sarcoidosis patients considering auto/immunological pathogenesis, and therapy with corticoids, immunosuppressive, and anti-TNF-α agents may suggest the need for prophylaxis." (PMID 40217830, 2025). "A hallmark of active sarcoidosis is the predominant expression of interferon-gamma in the affected organs, accompanied by the involvement of active cytokines, such as IL-2, IL-12, and tumor necrosis factor-alpha." (PMID 39598118, 2024). "Previous studies have suggested that polymorphisms in genes responsible for TNF-α production may have prognostic implications for the course of sarcoidosis." (PMID 39061958, 2024). "Taken together, we confirmed the association of rs4143332 at HLA-B and rs1800629 at TNF locus with acute onset of sarcoidosis in the Serbian sub-cohort and describe potential genetic links with several clinical features, including the recently described phenotypes of organ involvement." (PMID 37621457, 2023).
sarcoidosis (continued). "Notably, other TNF inhibitors have been shown to be ineffective for the treatment of sarcoidosis or can paradoxically cause sarcoidosis-like drug reactions, suggesting that further study of the use of TNF inhibitors to treat sarcoidosis is needed." (PMID 37021060, 2023). "Many association studies have attempted to identify genetic susceptibility in sarcoidosis, and various genes have been found to increase the risk of developing sarcoidosis, including chemokine receptors, tumor necrosis factor (TNF)-α, and several HLA loci and MHC class II antigens." (PMID 35141260, 2022). "Targeted treatment of underlying sarcoidosis with TNF-α inhibitors has the potential to repress sarcoidosis burden and thereby might partially normalize immune cell frequencies and halt PML progression in these patients." (PMID 34993476, 2022). "Tumor necrosis factor alpha inhibitors may cause tuberculosis or sarcoidosis by reactivating latent M. tuberculosis or P. acnes at sites with latent infection." (PMID 33801218, 2021). "Meta-analyses showed that TNFα -308 G and -238 G alleles predicted good response to anti-TNFα therapy, and this prediction was more powerful for etanercept than for infliximab in patients with spondyloarthritis or refractory sarcoidosis." (PMID 33540543, 2021). "Aside from sarcoidosis, TNF-α imaging may also prove useful for diagnostic and monitoring purposes in other TNF-mediated diseases." (PMID 32582173, 2020). "Interestingly, genetic variants in TNFα gene, as a susceptibility factor for sarcoidosis, have been replicated across populations in various studies (Fingerlin, Hamzeh and Maier, 2015;) and some of them have been also verified in meta-analyses." (PMID 31182092, 2019). "However, many anti-TNF-associated cases of sarcoidosis have also been reported, negating its therapeutic usage." (PMID 31731423, 2019). "There have been reports of 47 anti-TNF-associated cases of sarcoidosis until 2012." (PMID 26425632, 2015). "However, according to case reports anti-TNF agents, which are among the possible options for refractory sarcoidosis treatment, cause granulomatous lesions." (PMID 26425632, 2015). "Variants of the TNF gene confer a 1.5-fold increased risk of having sarcoidosis." (PMID 26464848, 2013). "Our data suggest that serum TNF-α may provide some diagnostic information regarding neurologic disease in African-American sarcoidosis patients." (PMID 22195005, 2011). "Interestingly, corticosteroid resistance in patients with sarcoidosis has been associated with exaggerated TNF-α release by alveolar macrophages, arguing for the potential use of alternative therapies (such as a TNF antagonist) to augment response and decrease steroid dose." (PMID 38337432, 2024). "Furthermore, literature reports have associated sarcoidosis with the use of medications such as immune checkpoint inhibitors, highly active antiretroviral therapy, interferons, and tumour necrosis factor-alpha (TNF-α) antagonists." (PMID 39180528, 2024). "However, it is worth noting that these transcription factors have established roles in DNA damage repair, cell proliferation, cell differentiation, and TNF and interferon inflammatory pathways in malignancies and infections previously associated with sarcoidosis." (PMID 36311769, 2022). "The single-nucleotide polymorphism (SNP) rs1800693 in the tumor necrosis factor receptor 1 (TNFR1) gene leads to the formation of a protein-mimicking effect of TNF-α inhibitors, which are agents used to treat sarcoidosis." (PMID 42086639, 2026). "Gene set enrichment analysis (GSEA) revealed significant enrichment of genes related to ‘TNF alpha signalling via NF‐κB’ in patients with active TU and sarcoidosis compared with controls." (PMID 40469525, 2025). "We found a prominent TNF‐based inflammatory phenotype that paralleled disease activity in both TU and sarcoidosis." (PMID 40469525, 2025).
sarcoidosis (continued). "Recent studies have found that the pathological mechanisms of sarcoidosis also involve other pro-inflammatory factors (such as TNF-α) and multiple signaling pathways (such as mTOR and JAK-STAT pathway)." (PMID 39904950, 2025). "The relationship between TNF-α inhibitors, such as infliximab, and the onset of sarcoidosis is a topic of ongoing interest." (PMID 40351964, 2025). "Case reports have documented regression of sarcoidosis after stopping anti-TNF therapy with adjunctive corticosteroids." (PMID 41107632, 2025). "Even if anti-TNF-α biologics are recommended as third-line therapy for sarcoidosis, paradoxically, some patients have experienced worsening of pre-existing sarcoidosis, such as uveitis or cutaneous sarcoidosis." (PMID 40647656, 2025). "In studies investigating the efficacy of TNF-α inhibitors (Infliximab and Adalimumab) in treating sarcoidosis, some cases have shown suboptimal responses." (PMID 39904950, 2025). "Sarcoidosis patients had decreased levels of IL-1β, IL-5, IL-8, IL-12p70, TNF-α, angiogenin, C3a, C4a, RANTES, and MCP-1 and increased levels of IL-2, IL-4, IL-6, IL-13, IFN-γ, and VEGF." (PMID 40725075, 2025). "In multiple randomized controlled trials, targeted therapy directed against TNF-α for sarcoidosis treatment has shown promising application potential." (PMID 39904950, 2025). "Targeted biologics such as Infliximab and Adalimumab can be used to target TNF-α for treatment of sarcoidosis when corticosteroids and immunosuppressor are ineffective." (PMID 39904950, 2025). "There are theories regarding a link between sarcoidosis and cytokines, including Th1, IL-2, IL-6, IL-8, IL-12, IL-18, IL-27, interferon gamma, and tumor necrosis factor." (PMID 40259952, 2025). "Several case reports and case series in the literature document instances of TNF-α inhibitor-induced sarcoidosis." (PMID 40351964, 2025). "At the moment, the first line of treatment for sarcoidosis is based on corticosteroids; second line on cytotoxic drugs and the third line on anti-tumor necrosis factor (TNF) biologics." (PMID 40400623, 2025). "Tumor necrosis factor-alpha (TNF-alpha) is a critical cytokine involved in the pathophysiology of sarcoidosis." (PMID 41026325, 2025). "Because of the central role of tumor necrosis factor alpha (TNF-α) in the pathophysiology of the granulomatous inflammation, TNF-α antagonists as infliximab have become a promising and increasingly used treatment in sarcoidosis and NS." (PMID 39812656, 2025). "Another study reported that 90 patients receiving different anti-TNF-a therapies (etanercept: 59%, adalimumab: 23% and infliximab:18%) all developed sarcoidosis-like lesions which was attributed to anti-TNF-a therapy." (PMID 40996589, 2025). "Tumour necrosis factor-α (TNF- α) antagonists are considered a significant therapeutic option in the treatment of sarcoidosis." (PMID 39180528, 2024). "Currently, the treatment for sarcoidosis includes first-line use of corticosteroids, followed by cytotoxic drugs as second-line treatment, and anti-tumor necrosis factor (TNF) biologics as third-line agents." (PMID 38611622, 2024). "For refractory sarcoidosis, TNF-α antagonists are regarded as an effective third-line therapy option." (PMID 39180528, 2024). "In sarcoidosis, this immune response involves T helper 1 (Th1) cells reacting to an antigen, which leads to the production of cytokines, primarily tumor necrosis factor-alpha." (PMID 39559588, 2024). "Several studies have evaluated sarcoidosis patients treated with TNFα blockers, either alone or in combination with other immunosuppressants." (PMID 38256476, 2024). "Since TNF plays a crucial role in the formation and maintenance of sarcoid granulomas, adalimumab and other anti-TNF agents are used in the treatment of sarcoidosis." (PMID 39881908, 2024).
sarcoidosis (continued). "Development of sarcoidosis during or immediately after chemotherapy is rare since most of the reported drugs have been antiretroviral therapy, tumor necrosis factor-α antagonists, interferons, and immune checkpoint inhibitors." (PMID 39044892, 2024). "Curiously, however, these TNF antagonists can also induce a paradoxical response known as a sarcoidosis-like reaction." (PMID 39881908, 2024). "Etanercept, a TNF receptor antagonist, was shown to be ineffective for sarcoidosis, as were other biologics such as golimumab (anti-TNF) and ustekinumab (an antibody to IL-21/IL-23)." (PMID 38337432, 2024). "Only 1 patient had sarcoidosis in our literature review, but anti-TNFα prescription is less common in this indication." (PMID 38957691, 2024). "Because of the large role that TNF-α plays in the proliferation of granulomatous inflammation, impeding the action of the cytokine would suggest a beneficial effect in the treatment of sarcoidosis." (PMID 38337432, 2024). "Th1 and Th17.1 cells in sarcoidosis-affected skin induced NF-κB–associated inflammatory genes, including LTB, TNF, CCR6, and IL6." (PMID 39225100, 2024). "Infliximab is a humanized monoclonal antibody that neutralizes TNF-α, and has the most robust data for the treatment of sarcoidosis." (PMID 37959167, 2023). "TGFB2 and KDR variants were reported to be associated in a German cohort with an acute course of sarcoidosis and variants of TNFRSF1B are known to influence the response to anti-TNF therapy in sarcoidosis." (PMID 37621457, 2023). "In patients with sarcoidosis, worsening of the disease during TNF-a antagonist therapy is difficult to interpret, particularly given the paucity of relevant information in the literature." (PMID 37250639, 2023). "A large-scale study on the effects of TNF inhibitors in refractory sarcoidosis has shown a staggering rate of adverse events." (PMID 37334374, 2023). "There are also reports on an analgesic effect of anti-TNF therapy in patients with SFN due to sarcoidosis." (PMID 36604634, 2023). "Infliximab is a monoclonal antibody (mAb) targeting TNFα that is being used off-label to treat sarcoidosis." (PMID 37021060, 2023). "In cases where neuro-sarcoidosis is still active or relapses while on glucocorticoids and a second-line agent, Tumor necrosis factor (TNF)-alpha inhibitor- infliximab is the preferred medication, and adalimumab is recommended as an alternative to infliximab." (PMID 37568942, 2023). "Anti-TNF therapy has been shown to improve lung function in a subset of sarcoidosis patients with active nodular lung inflammation on X-ray." (PMID 37021060, 2023). "Five of those were inversely correlated with suppressive function of Tregs in sarcoidosis, and six (TNFα, TNFR I and II, sCD25, Ki-67 and number of Tregs) were particularly upregulated or increased in subjects with thoracic lymphadenopathy." (PMID 38173720, 2023). "Treg expansion is stimulated by TNF-α, and patients with severe and progressive sarcoidosis have higher PB TNF-α levels than patients with milder and stable disease, providing a basis for escalating expansion of Treg." (PMID 37161980, 2023). "Targeted TNF therapy was the first biological therapy prescribed to patients with sarcoidosis because TNF-α is secreted by macrophages in patients with active sarcoidosis, and plays a key role in the development of sarcoid granuloma." (PMID 37109576, 2023). "Despite data supporting the use of TNF-a antagonists to treat sarcoidosis, these drugs have been reported to induce sarcoid-like reactions." (PMID 37250639, 2023). "Banse 2013 evaluated the efficacy and safety of three TNF inhibitors to treat joint manifestations of sarcoidosis." (PMID 35943526, 2022). "In sarcoidosis, unstimulated sarcoid-derived alveolar macrophages have been shown to intrinsically produce increased amounts of IL-1 and TNF-α." (PMID 35141260, 2022).
sarcoidosis (continued). "The total duration of TNF inhibitor exposure was 17.6 patient-years, which was started a median of 3 (0.33–17) years after sarcoidosis diagnosis." (PMID 35943526, 2022). "In contrast to broadly acting immunosuppressants, another frequently used therapy for sarcoidosis is infliximab, a chimeric monoclonal antibody directed against TNF-α." (PMID 34993476, 2022). "We also found that the activity of other cytokines including GM-CSF (JAK2), IL-15 (JAK1/3), IL-6 (JAK1/2), IL-12 (JAK2/TYK2) and TNF (JAK-independent) are also evident in sarcoidosis." (PMID 35668129, 2022). "Infliximab is a monoclonal antibody that binds and neutralizes circulating tumor necrosis factor-alpha, a key inflammatory cytokine in the pathophysiology of sarcoidosis." (PMID 35264154, 2022). "The conventional treatment for sarcoidosis is corticosteroid medication, which prevents the generation of cytokines including interlukin-2 (IL2), interferon (IFN), and tumor necrosis factor (TNF), causing granulomatous lesions to regress." (PMID 37483534, 2022). "Other genes associated with immune regulation of sarcoidosis, including NOTCH4, TNFα, NOD2, and ANXA11, were also detected by GWAS analysis in different races." (PMID 35860586, 2022). "COVID-19 and sarcoidosis share cytokine-releasing patterns: high levels of IL-6, IL-10, TNF-α, and IFN-γ are common in both diseases." (PMID 36148452, 2022). "Meanwhile, they confirmed that the tumor necrosis factor (TNF), toll-like receptor signaling, and IL-17 signaling pathways were involved in the sarcoidosis pathobiology from KEGG pathway enrichment analysis." (PMID 35860586, 2022). "Taken together, these results suggest that TNF is an important mediator in the pathogenesis of sarcoidosis." (PMID 36405616, 2022). "Together, the results of the present study support those of previous studies that indicate a central role of IL-1 and TNF signaling in sarcoidosis." (PMID 35141260, 2022). "The pathogenesis of sarcoidosis is associated with CD4 + T Cell activation, and secretion of cytokines including interferon-γ, tumor necrosis factor (TNF)-α, and transforming growth factor-β." (PMID 33539409, 2021). "As sarcoidosis is predominantly a T-helper cell mediated disease, mitigation of inflammation with use of corticosteroids, antimalarials, TNF-α antagonists, among others, has been a mainstay of treatment." (PMID 33718397, 2021). "In the lung of patients, these cells are an important source of TNFα, a major cytokine in the pathogenesis of sarcoidosis." (PMID 34456926, 2021). "Tumour necrosis factor α (TNF-α) is pivotal in sarcoid granuloma formation, and inhibitors of TNF-α offer an attractive third-line treatment option in sarcoidosis." (PMID 34233893, 2021). "As with RA, active sarcoidosis is characterized by an overexpression of many pro-inflammatory cytokines (e.g., tumor necrosis factor-α, interleukin-1 and inteleukin-6) that can induce a significant impairment of the left atrial and ventricular function." (PMID 34685436, 2021). "In a separate assay, one of the two sarcoidosis subjects whose BAL was analyzed by flow cytometry showed a similar change—a small increase in TNF-α and a larger increase in IL-10." (PMID 31963936, 2020). "A prospective study included 56 severe sarcoidosis patients, refractory to first- and second-line treatment, who were treated with the anti-TNF drug infliximab." (PMID 32760396, 2020). "The choice to switch anti-TNF alpha biologics in patients with rare IMIDs, particularly in sarcoidosis, requires well-considered decision-making and accurate monitoring due to a possibly higher incidence of disease worsening." (PMID 32850911, 2020). "At present, TNF antagonists can be considered standard-of-care therapy in severe cases of refractory sarcoidosis." (PMID 33330556, 2020). "TNF, which is readily produced by stimulated monocytes, is a key cytokine in sarcoid granulomas, and anti-TNF immunotherapy is deployed as treatment regimen for some sarcoidosis patients." (PMID 32948789, 2020).